AQP7P3 (aquaporin 7 pseudogene 3)
Synonyms: AQPap-3; LOC112267859
Gene: Transcribed unprocessed pseudogene on chromosome 9 (65,878,766 to 65,894,790, forward strand). Ensembl gene ENSG00000279688.
Diseases named in the same sentence as AQP7P3 in open-access papers:
AQP7P3 is named in the same sentence as 1 disease in open-access papers, as found by Europe PMC text mining. Sharing a sentence is not in itself a finding about the gene and the disease. The quoted sentences say what the papers report.
cardiac hypertrophy (1 paper, 2021). "AQP7P3 is the main aquaglyceroporin in the heart situated in between the capillary lumen and interstitial space that acts as a glycerol facilitator, and its dysfunction can lead to cardiac hypertrophy and death." (PMID 33810615, 2021).